POLE (DNA polymerase epsilon, catalytic subunit)
Diseases named in the same sentence as POLE in open-access papers (continued):
Sharing a sentence is not in itself a finding about the gene and the disease.
endometrial cancer (continued). "Identifying these 11 pathogenic variants in the POLE gene is critical to determining a positive prognosis and preventing overtreatment in endometrial cancer." (PMID 37627129, 2023). "Previous studies have shown that endometrial cancer patients with a mutated POLE gene display high-risk features, such as tumors with a high-grade molecular subtype, and have exceptionally favorable survival outcomes." (PMID 38136273, 2023). "Detection of 11 pathogenic variants in the POLE gene in endometrial cancer (EC) is critically important to identify women with a good prognosis and reduce overtreatment." (PMID 37229628, 2023). "The POLE mutated/ultramutated group of endometrial cancers has a high tumour mutation burden, tumour neoantigen production, and tumour-infiltrating T cells." (PMID 37958329, 2023). "Somatic alterations in the exonuclease domain of POLE occur in a subgroup of endometrial cancers with ultra-mutation (frequently ≥100 mutations/Mb) and excellent clinical outcome; the former was replicated in the C-CAT cohort and the latter in the NCCH cohort." (PMID 36797358, 2023). "Somatic POLE exonuclease domain mutations (EDMs) have been reported in 7–12% endometrial cancers (ECs) and defined a subgroup of endometrial cancers with ultrahigh somatic mutation frequencies, high tumor infiltrated lymphocytes and favorable outcomes." (PMID 36765365, 2023). "There are four TCGA molecular subtypes of endometrial carcinomas: POLE mutated, MSI-H, copy-number low, and copy-number high." (PMID 36936912, 2023). "Four molecular groups have been recently defined for endometrial carcinomas: the hypermutated (mismatch repair deficiency), the ultramutated (POLE mutated), the copy-number low (CN-low), and the copy-number high (CN-high) groups." (PMID 37377900, 2023). "The patients with POLE mutations had a high immune response and good prognoses in endometrial carcinoma." (PMID 36936374, 2023). "Endometrial carcinoma is classified into four categories: POLE ultra-mutated, microsatellite instability (MSI) hyper-mutated, copy number low and copy number high." (PMID 36928660, 2023). "These hotspot EDMs are associated with the malignant behavior of endometrial cancer cells in vitro and favorable prognosis in patients, suggesting that POLE affects a wide range of cellular processes beyond DNA replication and proofreading." (PMID 36313640, 2022). "Somatic POLE exonuclease domain mutations (EDMs) occur in 7–12% of endometrial cancer cases, with P286R and V411L representing the most common pathogenic POLE EDMs, followed by S297F, A456P, and S459F." (PMID 36313640, 2022). "It has been recommended that patients with POLD1 and POLE variants undergo regular colonoscopic and gastroscopic surveillance, in addition to screening for endometrial cancer." (PMID 35128723, 2022). "Further, POLE mutation that is associated with improved prognosis in high‐grade tumors is less frequently found in low‐grade, early‐stage endometrial cancers as suggested here and by previous studies." (PMID 36169332, 2022). "The tenth signature among these was linked to PolE mutations found in colorectal cancer and endometrial cancer." (PMID 35326618, 2022).
endometrial cancer (continued). "Kaplan-Meier analysis showed that patients with EDMs had significantly better PFS and OS than the rest of the cohort, suggesting a complex relationship between POLE mutations and the pathogenesis of endometrial cancer." (PMID 36313640, 2022). "In this study, in addition to the most common pathogenic POLE EDMs P286R and V411L, we identified two new hotspot DEMs R375Q and P452L in patients with aggressive endometrial cancer subtypes." (PMID 36313640, 2022). "It has been suggested that somatic POLE EDMs are early events in endometrial cancer because the presence of a POLE mutation leads to an extremely high mutation load in precancerous lesions and thus accelerates their transition to cancer." (PMID 36313640, 2022). "Specific to endometrial cancer, the POLE-mutated phenotype exhibits an extremely high mutation rate with an average of 232 mutations/Mb." (PMID 35158899, 2022). "By MTT assay, we found that overexpression of POLE-P286R, R375Q, and P452L significantly increased IC50 values of cisplatin compared with overexpression of wildtype POLE, suggesting that the hotspot mutations induce cisplatin resistance in endometrial cancer." (PMID 36313640, 2022). "PolE mutations are most frequently found in colorectal cancer (1–3%) and endometrial cancer (6–12%), and rarely found in lung, breast, brain, prostate, kidney, ovarian, bone, and gastric cancers." (PMID 35326618, 2022). "We characterized the of hotspot exonuclease domain mutations in the DNA polymerase ε gene and identified P286R, V411L, R375Q, and P452L as pathogenic POLE hotspot EDMs in endometrial cancer." (PMID 36313640, 2022). "To explore the presence of POLE variants and their association with clinical outcomes in endometrial cancer, we retrospectively analyzed the tumor samples and clinical characteristics of 146 patients with endometrial cancer." (PMID 36313640, 2022). "In 2013, The Cancer Genome Atlas (TCGA) Research Network found four molecular subgroups of endometrial carcinoma: POLE mutated/ultramutated, microsatellite unstable/hypermutated, copy number high, and copy number low." (PMID 35892892, 2022). "This study was designed to investigate the frequency and clinicopathological characteristics of POLE-mutated/ultramutated (POLEmut) in endometrial carcinoma (EC) and assess the prognostic values of POLE status." (PMID 36357827, 2022). "Somatic mutations in the exonuclease domain of POLE have been identified in 7–12% of uterine endometrial cancers, in 1–2% of colorectal cancers, and at low frequencies in stomach cancer, glioblastoma, breast cancer, and others." (PMID 34158040, 2021). "Integrated genomic characterization by the Cancer Genome Atlas (TCGA) in 2013 defined four distinct endometrial cancer subgroups (POLE mutated, microsatellite instability, low copy number, and high copy number) with possible prognostic value." (PMID 34540651, 2021). "As an approach to investigate how ultra-mutator Pol ε mutants exert their genotoxic activities in vivo, we focused on POLE alleles originally described as drivers of colorectal and endometrial cancers." (PMID 33764464, 2021).
endometrial cancer (continued). "It is worth noting that POLE-mutated cases have shown a high rate of response to immunotherapy in tumors of other sites, such as colorectal and endometrial cancers, and as such, this should also be explored for PDAC." (PMID 34206554, 2021). "Studies have indicated that tumorous lesions other than colorectal cancer include duodenal adenomas or central nervous system tumors in POLE gene variants and endometrial cancer, breast cancer, and central nervous system tumors in POLD1 gene variants." (PMID 34185173, 2021). "Somatic and germline mutations in the proofreading domain of the replicative DNA polymerase ε (POLE-exonuclease domain mutations, POLE-EDMs) are frequently found in colorectal and endometrial cancers and, occasionally, in other tumours." (PMID 34228709, 2021). "The amino-acids substituted in somatic POLE EDMs show a variable incidence rate, with POLE-P286R being the most frequent variant in colorectal and endometrial cancer, reaching a frequency of ~7% in early-onset colorectal cancer." (PMID 34228709, 2021). "The proportion varied widely across tissues, for example it is 2% on average in endometrial cancers (UCEC) of patients with POLe mutations to 87% in pancreatic cancer (PAAD) patients who smoke." (PMID 33491650, 2021). "We trained models to predict histological subtypes, CNV-H subtype from the entire cohort and the endometrioid patients, CNV-L subtype, MSI-high subtype, POLE subtype, and the mutation status of 18 endometrial carcinoma-related genes." (PMID 34622237, 2021). "In endometrial cancer, survClust confirmed a previously known ultra-high mutated subtype associated with the POLE mutation signature (c2) and a hypermutated microsatellite instability (MSI) (c4) subtype." (PMID 33272320, 2020). "POLE is a tumor suppressor gene involved in nucleotide excision repair, which is mutated in 7–15% of endometrial cancers and is associated with a good prognosis and a high TMB." (PMID 33378353, 2020). "Recent studies reported that POLE-mutated endometrial cancer was characterized by robust tumor T-cell infiltration." (PMID 32457342, 2020). "POLE-mutated endometrial cancers have been reported to be MSS in a couple of studies including this article." (PMID 32066405, 2020). "Endometrial cancer (EC) harboring heterozygous POLE proofreadinginactivating mutations (POLE-exo*) is associated with anincreased number of somatic mutations that result in a distinctive anti-tumorimmune response." (PMID 33001133, 2020). "Thirty six percent of colorectal, stomach and endometrial cancers with POLE mutations carried additional mutations in POLQ (E/Q), POLZ/REV3L (E/Z) or both DNA polymerases (E/Z/Q)." (PMID 32838755, 2020). "Patients with endometrial carcinoma and POLE mutations have improved responses to treatment, and the POLE mutant subtype has better predictive value than the MSI subtype." (PMID 32000802, 2020). "Pathogenic somatic missense mutations within the DNA polymerase epsilon (POLE) exonuclease domain define the important subtype of ultramutated tumours (‘POLE‐ultramutated’) within the novel molecular classification of endometrial carcinoma (EC)." (PMID 31829442, 2020). "In order to compare the mutation rate and total TMB between the studied tumor andendometrial cancers with heterozygous POLE-exo* mutations, wedownloaded 25 exomes of endometrial carcinoma from ICGC portal withPOLE-exo* somatic mutations and absence of MSI." (PMID 33001133, 2020). "One out of 25 endometrial carcinomas harbored theheterozygous POLE-exo* S459F and presented a rate of 167 mutations/Mb." (PMID 33001133, 2020).
endometrial cancer (continued). "Patient survival curves showed high expressions of AMFR/gp78 and low expression of POLE, which were associated with the favorable prognosis of endometrial cancer patients." (PMID 31864301, 2019). "In endometrial cancer, somatic POLE proof-reading mutations were found in about 7% ECs, and the results have shown a tight association with high histologic grade." (PMID 31864301, 2019). "GSEA using Gene Ontology (GO) terms as the gene sets showed the enrichment in categories like glucose metabolic process, isomerase activity, exonuclease activity, and intramolecular transferase activity in endometrial cancer samples with POLE mutations." (PMID 31864301, 2019). "Consistent with our study, somatic mutations in the POLE gene were associated with immune cell infiltration, eliciting an antitumor immune response in endometrial cancer patients." (PMID 30847026, 2019). "In endometrial cancer patients with POLE mutations, the expression of AMF/PGI was slightly higher than that in patients with wild type POLE (FC = 1.2, P = 0.00077)." (PMID 31864301, 2019). "POLE mutations have been identified in 7–12% of endometrial cancers (EMCA), as well as in 1–2% of colorectal cancers, and have been described in rare cases of breast, pancreatic, stomach, lung, ovarian, and brain tumours." (PMID 30917185, 2019). "The results of the GSEA also confirmed that cellular glucose metabolism was significantly enriched in endometrial cancer patients with POLE mutations, suggesting a possible approach to improving the prognosis of endometrial cancer through POLE mutation." (PMID 31864301, 2019). "Previous results suggest that POLE mutational status was associated with tumor mutational burden in endometrial cancers consistent with our finding." (PMID 31864301, 2019). "This study showed the POLE mutations a vital factor in endometrial cancer patients, leading to a higher expression of AMF/PGI and AMFR/gp78." (PMID 31864301, 2019). "The results suggest that POLE mutations can significantly improve the prognosis of endometrial cancer patients and 15% of patients (Number = 80) possessed POLE somatic mutations." (PMID 31864301, 2019). "Mutations in the exonuclease domain of POLE have been confirmed to be significantly associated with favorable prognosis and improved progression-free survival in endometrial cancer." (PMID 31864301, 2019). "The comprehensive high expressions of AMFR/gp78 and low expression of POLE were associated with the favorable prognosis of endometrial cancer patients." (PMID 31864301, 2019). "POLE was the 123rd most frequently mutated gene in endometrial cancer with a mutational frequency of 80 in the 530 tumor samples (15%)." (PMID 31864301, 2019). "In this study, we identified the existence of somatic POLE mutations in 80 cases of large sporadic individuals in the 530 endometrial cancer samples in the TCGA-UCEC project." (PMID 31864301, 2019). "Mutations in the exonuclease domain of POLE have been reported to improve progression-free survival in endometrial cancer." (PMID 31864301, 2019). "Taken together, POLE mutations improve the prognosis of endometrial cancer via regulating cellular metabolism through AMF/AMFR signal transduction." (PMID 31864301, 2019). "Though POLE mutations in higher-grade meningioma have only recently been reported in prior work, POLE mutations have been linked to worse prognosis in other cancers such as in particular subgroups of colorectal and endometrial cancer patients." (PMID 31191822, 2019). "The results showed that endometrial cancer patients with low histologic grade (G1), early clinical stage (I+ II), and POLE mutations had favorable prognosis." (PMID 31864301, 2019). "Early studies demonstrated that POLE mutations were observed in colorectal cancer, pancreatic cancer, ovarian cancer, ultra-mutated giant cell high-grade glioma, and endometrial cancer." (PMID 31864301, 2019).
endometrial cancer (continued). "POLE mutational status was proven to be an independent prognostic factor for endometrial cancer patients." (PMID 31864301, 2019). "In a study of hypermutated endometrial cancers (>232 × 10−6 mutations/Mb), tumors with somatic POLE mutations were associated with a 15-fold higher number of neoepitopes per sample when compared to tumors with microsatellite instability (MSI)." (PMID 31645345, 2019). "One novel objective of this study was to establish the possible relationship between POLE mutations and endometrial cancer prognosis." (PMID 31864301, 2019). "The results showed that cellular glucose metabolism such as glycolysis and gluconeogenesis were significantly enriched in endometrial cancer samples with POLE mutations." (PMID 31864301, 2019). "We identify four molecular subtypes that resemble those observed in endometrial carcinoma: POLE-mutated, microsatellite instability, copy number high, and copy number low subtypes." (PMID 31672974, 2019). "The ovarian CS and endometrial carcinoma share a subset of SNVs/indels, including the POLE p.P286R mutation." (PMID 31672974, 2019). "Our evidence suggests that, in sporadic colorectal and endometrial cancers with pathogenic somatic POLE mutations, the POLE mutation is antecedent to either of these events." (PMID 29604063, 2018). "Screening of the 3′-5′ exonuclease domains of POLE (residues 268–471) in 173 endometrial cancers resulted in the identification of 13 non-synonymous variants in POLE." (PMID 29301327, 2018). "The number of precursor lesions informative for detailed analysis was limited, in keeping with the relative rarity of POLE mutations in endometrial cancer, and the frequency with which precancerous and cancerous lesions occur in the same tumour section." (PMID 29604063, 2018). "In the TCGA series, POLE mutations were found in 3% of colorectal cancers and 7% of endometrial cancers (ECs)." (PMID 29599905, 2018). "This was also the case in 17 of 17 endometrial cancers and 12 of 13 colorectal cancers with pathogenic POLE mutations from the TCGA series." (PMID 29604063, 2018). "Recent studies proposed to classify endometrial cancers into 4 categories: POLE ultra-mutated, microsatellite instability hyper-mutated, copy number-low, and copy number-high." (PMID 29426295, 2018). "The Cancer Genome Atlas (TCGA) research network recently identified an ultra-mutated group of endometrial carcinomas characterized by mutations in POLE and exceptionally high substitution rates." (PMID 29599905, 2018). "In fact, the tumors which did not exhibit losses of CR genes had far higher mutation rates across all mutation types, consistent with POLE and microsatellite mutations driving tumorigenesis in many endometrial cancer patients." (PMID 27391266, 2016). "Somatic or germline mutations in the exonuclease domain of the POLE gene cause hypermutated CRCs (∼3%) or endometrial cancers (∼7%)." (PMID 27612425, 2016). "Endometrial cancers (ECs) with POLE proofreading mutations are typified by ultramutation and excellent prognosis." (PMID 27141333, 2016). "Third, even in endometrial cancers in which the mutational frequency of POLE is relatively high, the mutational frequencies of other mutations in the exonuclease domain of POLE are extremely low (i.e., usually <5%)." (PMID 27612425, 2016). "Somatic exonuclease domain mutations in POLE gene have been identified in colorectal and endometrial cancer patients, and show an association with hypermutability and microsatellite stability." (PMID 26302849, 2015). "Recently, POLE mutations were also detected in 7–12% endometrial cancers and were also associated with favorable prognosis." (PMID 26517354, 2015).